INS (insulin)
Diseases named in the same sentence as INS in open-access papers (continued):
Sharing a sentence is not in itself a finding about the gene and the disease.
diabetes (continued). "Diabetes mellitus Type 1 results from severe insulin deficiency while diabetes mellitus type 2 is characterized by insulin resistance, which may be merged with relatively reduced insulin secretion." (PMID 30834086, 2019). "Moreover, pre-diabetes is initiated by underlying processes that we will call pre-pre-diabetes, which arise while fasting glucose levels and glucose tolerance are still normal, though insulin levels are increased (hyperinsulinemia), indicating mild insulin resistance." (PMID 30448823, 2018). "Furthermore, BCAAs are associated with insulin sensitivity and the development of diabetes." (PMID 28936587, 2018). "However, fructose intake exceeding 250 g/day and providing an excess of calories may reduce hepatic insulin sensitivity in healthy, obese or genetically at-risk individuals for diabetes." (PMID 29914103, 2018). "Given the association of diabetes, insulin treatment, and cell proliferation, our specific goal was to determine whether the liver in the diabetic state presents a greater response to DEN-induced cell cycle alteration, which is essential for the malignant transformation." (PMID 29850590, 2018). "Diabetes mellitus is characterized by a group of metabolic disorders such as hyperglycemia over a long period, impaired carbohydrate, lipid, and protein metabolism caused by pancreas's failure to produce enough insulin, and insufficiency of the cells responding properly to the produced insulin." (PMID 30116491, 2018). "Diabetes mellitus (DM) is a metabolic disease caused by an insulin secretion deficiency or insulin dysfunction, which leads to hyperglycemia." (PMID 35539960, 2018). "There are two principal types of DM, characterized either by an absolute deficiency of insulin (type 1 diabetes), or resistance to the effects of insulin (type 2 diabetes; T2D)." (PMID 29316644, 2018). "Diabetes mellitus (DM) is a metabolic disorder categorized with relative (type 2) and absolute (type 1) deficiency of glucose regulatory hormone—insulin." (PMID 29854822, 2018). "Diabetes mellitus is an endocrine metabolic disorder characterized by abnormal increase in the blood sugar level (hyperglycaemia) as well as alteration in lipids, carbohydrates, and protein metabolism, which is linked to low level of insulin production or insensitivity of target organs to insulin." (PMID 29364169, 2018). "Being gainfully employed was associated with higher knowledge of insulin use (p = 0.013), while attending DM classes was significantly associated with general knowledge about diabetes (p = 0.026)." (PMID 30050608, 2018). "Diabetes mellitus (DM) is a chronic metabolic disorder caused by either impaired insulin secretion or insulin action, or both." (PMID 29534427, 2018). "However, we must keep in mind that fatty pancreas is at least a risk factor for impaired insulin secretion and might be a clinical sign of diabetes." (PMID 30571730, 2018). "Type 2 diabetes mellitus is an acquired syndrome characterized by several defects in the regulation of glucose homeostasis, including elevated blood glucoside levels, increased hepatic glucose production, deficient insulin secretion, insulin resistance, and/or pancreas β-cell dysfunction." (PMID 30103438, 2018). "Indeed, in DEVOTE, the trial population was at particularly high risk of MACE and fatal events, with a long duration of diabetes (> 16 years) and previous insulin use (85%), and the majority of participants with established cardiovascular or chronic kidney disease (85%)." (PMID 28913543, 2018). "The Wnt, MAPK, TGF-beta and insulin signaling pathways are known to regulate insulin sensitivity, lipid metabolism, glucose and energy homeostasis; the axon guidance pathway is associated with Wnt proteins; and the tight junction pathway is related to the pathophysiology of diabetes." (PMID 29503662, 2018).
diabetes (continued). "Diabetes mellitus (DM) is a metabolism disorder and exocrine system dysfunction that represent an insulin deficiency or resistance of cells for insulin hormone." (PMID 29301240, 2018). "The primary objective of this study was to assess factors associated with insulin adherence among Lebanese patients with diabetes and to explore the relationship between this adherence, the patients’ trust in their healthcare provider, and diabetes-related emotional distress." (PMID 29520741, 2018). "The largest randomized, multicenter clinical study, The United Kingdom Prospective Diabetes Study, was the first to demonstrate the ability of metformin to reduce the risk of macroangiopathy in patients with newly diagnosed diabetes and obesity or overweight, more than sulfonylureas or insulin." (PMID 30248910, 2018). "Because long-term exogenous insulin use in diabetes patients may have a greater impact on breast tissue than genetic predisposition to long-term elevations in endogenous insulin, it will also be relevant to assess potential differential associations by exposure type." (PMID 30092829, 2018). "Diabetes mellitus is a serious complex multifactorial disorder characterized by hyperglycemia (very high blood glucose level) and glucose intolerance, either due to the relative deficiency in insulin secretion or impaired the effectiveness of insulin's action to enhance glucose uptake." (PMID 30108655, 2018). "Hyperglycemia in diabetes mellitus state may be attributed to deficiency in insulin concentration, which triggers increase in blood glucose concentration and affecting activities of some carbohydrate metabolizing enzymes (glucose‐6‐phosphatase and hexokinase among others)." (PMID 29387371, 2018). "This is in line with the findings from the Finnish Diabetes Prevention Study, showing that the reduction in the risk of development of type 2 diabetes after a lifestyle intervention is related to improvement in insulin sensitivity, which has beneficial effects on preservation of beta-cell function." (PMID 29425120, 2018). "Therefore, the GK SAAC genes Ide, Ppp1r3c, Hdac9, Ghsr and Gckr with their specific mutations, may change the protein functions and improve insulin sensitivity in the prediabetes stage in GK rats and act as anti-diabetics in GK rats." (PMID 30687391, 2018). "In addition, the different responsiveness of separate chemotypes of primary sensory neurons to insulin may interfere with the development of pathologies associated with diabetes mellitus." (PMID 30364236, 2018). "Furthermore, Mdivi-1, a chemical compound which attenuates mitochondrial fission by selectively blocking GTPase activity of Drp1, reversed mitochondrial genotype-related imbalance of dynamics and ameliorated the impairment of insulin signal transduction in our diabetes-susceptible cybrid cells." (PMID 30363990, 2018). "Glucose metabolism disturbances, whether represented by fasting hyperglycemia, high insulin, increased fructosamine, elevated HbA1c or diagnosis of diabetes mellitus, may have been more steadily associated with cognitive impairments in older subjects than other components of MetS." (PMID 29579115, 2018). "Quantitative research should be undertaken into the effectiveness of healthcare interventions such as i) support groups, ii) education and iii) inviting SO to diabetes appointments and the physiological causes of everyday insulin and medication might have on HU patients." (PMID 30417151, 2018). "Consequently, it is plausible that aging in people with diabetes could be associated with abnormal ratios of glucagon to insulin with a subsequent impact on exercise capacity." (PMID 29720965, 2018). "The increased postabsorptive plasma 3-HIB levels in our subjects with diabetes may reflect increased protein breakdown as a consequence of relative insulin deficiency due to insufficient insulin secretion in relation to insulin resistance, which would also explain increased ketone body production." (PMID 29967793, 2018).
diabetes (continued). "These probably because patients with diabetes were more likely to had lipid metabolic disorders, which may be associated with insulin resistance and insulin sensitivity, while increasing serum lipids levels would lead to dysfunction of pancreatic β-cell function." (PMID 30581781, 2018). "In fact, diabetes mellitus is defined as a metabolic disorder, of various etiologies, characterized by the presence of chronic hyperglycemia accompanied by metabolism disruption of carbohydrate, lipid and protein, resulting from a defect in insulin secretion, its activity, or both causes." (PMID 30186783, 2018). "Diabetes mellitus (DM) is one of the fastest growing chronic diseases and is caused by a deficiency in insulin secretion or by ineffectiveness in insulin action." (PMID 29342975, 2018). "The two non-synonymous variants (H18R and A890V) in GK IDE protein contribute to reduced insulin-degrading activity by 31% which suggests that the GK fixed mutations in Ide may act as a compensatory molecule to protect GK from diabetes." (PMID 30687391, 2018). "Functional relevance of miRNA-143 in diabetes was described and discussed in genetic and diabetic mouse models: an increased expression in murine liver was detected, and miR-143 overexpression was associated with impaired insulin sensitivity and glucose homeostasis." (PMID 29358694, 2018). "Therefore, the interstitial fluid pH with little pH buffer in diabetes mellitus would be lower than that under the normal condition, and the lowered pH of the interstitial fluid is a causal factor for the attenuation of insulin signaling in the skeletal muscle." (PMID 30538991, 2018). "There are two main forms of diabetes mellitus including type 1, which has an unknown etiology and is characterized by a loss of insulin-producing β-cells in the pancreas resulting in the inability of the pancreas to produce enough insulin." (PMID 30534081, 2018). "Additionally, the association with insulin signaling and diabetes may signify a link to endothelial dysfunction, which has previously been described in BAV patients." (PMID 29426841, 2018). "Diabetes and obesity are associated with an enhanced expression of the soluble epoxide hydratase (sEH), a key enzyme in the degradation of EETs, and genetic deletion of sEH ensues an improved insulin sensitivity and an anti-apoptotic effect on pancreas islet cells in a murine diabetes model." (PMID 30360467, 2018). "In the intervention Diabetes Prevention Program study, circulating NTproBNP was associated with a measure of insulin sensitivity before and during preventive interventions regardless of whether a participant was treated with placebo, intensive lifestyle intervention or metformin." (PMID 28946871, 2017). "Diabetes mellitus (DM) is a metabolic disorder caused either by the insufficient production of insulin in islet cells of the pancreas or by resistance against secreted insulin in tissues, leading to an elevation in the glucose concentration in the blood." (PMID 28578411, 2017). "Beyond the impact of SSBs on energy balance and risk for obesity, the large blood glucose and insulin excursions that can result from SSB consumption may independently increase risk for the development of type 2 diabetes mellitus (T2D) and cardiovascular complications." (PMID 28956823, 2017). "Furthermore, diabetes control in puberty is modulated by a change in synthesis and secretion of several hormones, including growth hormone, which associate with changes in insulin sensitivity." (PMID 29238730, 2017). "Although use of insulin and hypoglycemic drugs is currently considered to be the main and effective treatment for diabetes mellitus, they may cause different complications such as increased lipid reserves, shrinkage of lipid at injection site, and hypoglycemic shock." (PMID 28975089, 2017).
diabetes (continued). "Additionally, diabetes is the quintessential life course disease, as its risk factors and its underlying pathophysiology of increased insulin resistance followed by decreased insulin secretion have been shown to span across the life cycle." (PMID 28293304, 2017). "Diabetes mellitus (DM) is a chronic metabolic disease caused by deficiency or diminished effectiveness of endogenous insulin." (PMID 29234049, 2017). "Some studies have suggested that reduced leptin levels in insulin-deficient diabetes may activate the hypothalamic-pituitary-adrenal (HPA) axis and that restoration of plasma leptin may attenuate hyperglycemia in large part by suppression of the HPA axis and reducing secretion of glucocorticoids." (PMID 29190687, 2017). "Given that we and others have shown the podocyte-specific knockdown of the IR induces albuminuria and glomerular disease, it is reasonable to predict that this insulin-induced IR loss could further contribute to renal disease in settings of diabetes and insulin resistance." (PMID 28852804, 2017). "Additionally, diseases such as insulin resistance, obesity, diabetes, and cancer may be associated with the deregulation of insulin-mediated angiogenesis." (PMID 28424632, 2017). "Obesity-associated diseases include diabetes mellitus (DM), insulin (INS) resistance, lipid profile abnormalities, orthopedic diseases, cardiorespiratory diseases, neoplasia, and shortened life span." (PMID 28261588, 2017). "Diabetes Mellitus (DM) is defined as a group of metabolic disorders mainly caused by abnormal insulin secretion and/or action." (PMID 28138367, 2017). "Indeed, the deficiency of Dicer (the enzyme responsible for miRNA maturation) in pancreatic β-cells leads to up-regulation of insulin transcriptional repressors, reduced insulin expression and secretion, loss of glucose homeostasis and diabetes development in mice." (PMID 29200427, 2017). "In addition to these associations, higher levels of insulin, gastric inhibitory polypeptide, and pancreatic polypeptide remained significantly associated with self-reported diabetes with a false discovery rate <5%, indicating that the assay was able to detect markers associated with diabetes." (PMID 28753646, 2017). "Insulin, monotherapy or combined therapy (per se or as indication of poor blood glucose control) and diabetes duration may play a role in the association between diabetes and cancer." (PMID 29070034, 2017). "Based on this evidence and on the role of LRP1 in cargo transport by endocytosis, there is no doubt that LRP1 dysregulation will affect important cell processes, and could be associated with disease states including diabetes, considering its effects on insulin and glucose metabolism." (PMID 29201005, 2017). "Diabetes mellitus (DM) is a chronic multifactorial disease, characterized by a decrease in glucose-stimulated insulin secretion caused by pancreatic β cells dysfunction." (PMID 29068419, 2017). "In addition, coffee consumption might be been associated with higher insulin sensitivity and a lower risk of type 2 diabetes mellitus, which is a known risk factor for colorectal cancer." (PMID 27078843, 2017). "Furthermore, the magnesium, potassium, trigonelline, and niacin in coffee have been associated with enhanced insulin sensitivity, which may prevent the progression of diabetes mellitus." (PMID 28143499, 2017). "Diabetes mellitus (DM) is a chronic endocrine syndrome resulting from a deficiency in pancreatic insulin production and/or insulin resistance in target tissues, leading to various abnormalities in carbohydrate, lipid, and protein metabolism." (PMID 28333071, 2017). "Insulin, monotherapy or combined therapy, per se or as an indication of poor blood glucose control, in addition to diabetes duration, may play a role in the association of diabetes and cancer." (PMID 29070034, 2017).
diabetes (continued). "DOX and diabetes individually have been demonstrated to cause the release of ROS that might lead to muscle fatigue and metabolic dysregulation, which are in accordance with our present findings of muscle atrophy and insulin signaling markers." (PMID 27512375, 2016). "We thus examined miRNA signatures in skeletal muscle of programmed insulin resistant rats, before the onset of obesity and in the absence of traditional risk factors, and unmedicated individuals who had been newly diagnosed with either pre-diabetes or type 2 diabetes." (PMID 27163678, 2016). "In addition, our present in vivo and ex vivo results confirm that the induction of insulin-deficient Diabetes in rats impairs long-bone microarchitecture, while disrupting BMPC multiphenotype potential (decrease in osteogenesis and chondrogenesis and increase in adipogenesis)." (PMID 27840829, 2016). "However, even with the state-of-the-art technology, and a well-calibrated system, patients must calibrate their CGM at least twice per day and determine an appropriate dose of insulin to inject at least four times per day in order to reach the American Diabetes Association’s goal of HbA1c < 7.0%." (PMID 30740333, 2016). "Diabetes mellitus (DM), commonly known as diabetes, is a metabolic disease caused by insulin deficiency (type I: insulin-dependent DM) or malfunctioning (type II: insulin resistance) in which cells fail to respond to insulin, resulting in the blockage of glucose uptake by cells." (PMID 27388225, 2016). "In addition to shared demographics (e.g., aging, comorbidities, and genetic factors), there are reports of common pathologies that link AD and diabetes, such as amyloid deposits, cardiovascular risk factors, inflammation, glucose toxicity, and changes in insulin metabolism." (PMID 27142529, 2016). "Interestingly, as previously discussed, longer rather than shorter chain phospholipids have been negatively associated with obesity and diabetes, and the hypoglycaemic effect of insulin has been shown to improve when phospholipids of reducing carbon numbers from C18 to C10 are involved." (PMID 27471436, 2016). "While not a widely accepted concept, some researchers suggest that some AD may even be considered a metabolic disease caused by insulin resistance in the brain, separate from diabetes (Riveraet al., 2005), raising yet again the need for an evidence-based definition for “brain insulin resistance”." (PMID 27303627, 2016). "Further studies on the ability of the bacteria to modulate insulin secretion are needed to understand the mechanism through which they could cause diabetes, in order to develop strategies for the prevention of insulin imbalance and for the implementation of new therapeutic approaches." (PMID 27631977, 2016). "Diabetes mellitus (DM) is a metabolic disorder characterized by chronic hyperglycemia linked with total or partial deficiencies in insulin secretion or function." (PMID 27525022, 2016). "Thus, our results highlight that inhibition of alpha cell glucagon production is one potential mechanism by which leptin might be effective in controlling hyperglycemia in individuals with diabetes caused by diminished insulin reserve." (PMID 28702245, 2016). "Diabetes mellitus (DM) is a chronic metabolic disease caused by the insufficient production of insulin from β-cells of the pancreas or reduced sensitivity of cells to insulin." (PMID 27196881, 2016). "For instance, in 1970 the first multicenter, head to head trial (University Group Diabetes Program) of T2D glucose-lowering treatments assessing CV outcomes was interrupted, as all oral drugs (tolbutamide, phenformin) seemed to increase CV risk in comparison to placebo or insulin." (PMID 27716274, 2016).